Y_RNA (Y RNA )
Gene: Miscellaneous RNA gene on chromosome 18 (23,024,596 to 23,024,703, forward strand). Ensembl gene ENSG00000223023.
Homologues: Orthologues: chimpanzee Y_RNA (97% identical). Paralogues in human: RNY1P5 (77% identical), Y_RNA (77% identical), RNY1P14 (76% identical), Y_RNA (76% identical), Y_RNA (75% identical), Y_RNA (74% identical), Y_RNA (73% identical), RNY1P6 (72% identical), Y_RNA (72% identical), RNY1P1 (71% identical), Y_RNA (71% identical), RNY1P15 (70% identical), and 89 more.